RETN (resistin)
Diseases named in the same sentence as RETN in open-access papers (continued):
Sharing a sentence is not in itself a finding about the gene and the disease.
metabolic syndrome (142 papers, 2006 to 2026). A cluster of metabolic risk factors for CARDIOVASCULAR DISEASES and TYPE 2 DIABETES MELLITUS. "Although this study examined adipokines only at the transcriptional level and found no significant group differences, clinical evidence indicates that decreased leptin and increased resistin levels are associated with malnutrition and dyslipidemia." (PMID 41156533, 2025). "This study has shown that, in a sample of Brazilian patients with psoriasis, resistin serum levels are elevated and associated with the presence of DM and metabolic syndrome and correlate with serum triglycerides and total cholesterol." (PMID 37355349, 2023). "Authors suggested that GG and GC genotypes of the resistin variant are associated with the risk of metabolic syndrome in the Tunisian cohort." (PMID 35565757, 2022). "To investigate the diagnostic value of resistin in horses, we studied three categories of animals: healthy controls, horses with inflammatory conditions, and horses with insulin dysregulation/metabolic syndrome." (PMID 35011183, 2021). "Adipokines like leptin, adiponectin, visfatin, and resistin have been identified as potential mediators of metabolic syndrome and associated with insulin resistance, central obesity, dyslipidemia, and hypertension in autoimmune disease." (PMID 30712132, 2019). "Serum resistin levels were also higher in obese study participants who suffered from hypertension and/or met the diagnostic criteria for the metabolic syndrome." (PMID 29213336, 2017). "This study examined the association of resistin gene polymorphisms, rs1862513 and rs3745368, and related haplotypes with the development of metabolic syndrome in a Han Chinese population." (PMID 29386698, 2017). "In support of our results a previous study identified that a resistin to adiponectin ratio was associated with T2D and Metabolic Syndrome (MS) risk." (PMID 27536890, 2016). "In a clinical study, the plasma resistin level was associated with coronary atherosclerosis independently of metabolic syndrome and CRP." (PMID 27649254, 2016). "Elevation of serum resistin levels in obesity also has been reported by several groups and is associated with metabolic syndrome, dyslipidemia and inflammatory markers." (PMID 26474157, 2015). "As we all know, hypertension is an important component of metabolism syndrome, which has been proved to associate with many adipokines including adiponectin, leptin, angiotensin, perivascular relaxation factors, and resistin." (PMID 24665369, 2014). "Although the discussion about metabolic effects of resistin in humans remains controversial, its association with parameters of the metabolic syndrome has been repeatedly documented." (PMID 23951331, 2013). "Correlative observations made in metabolic syndrome cohorts showed that resistin is strongly associated with hypercoagulative and hypofibrinolitic activities." (PMID 23721173, 2013). "Variants in the RETN gene correlate with signs of metabolic syndrome, T2DM, and BMI." (PMID 37888112, 2023). "Variants in the RETN gene correlate with signs of metabolic syndrome." (PMID 36983642, 2023). "The increase in resistin in horses with severe insulin dysregulation may be related to the inflammatory changes associated with metabolic syndrome." (PMID 35011183, 2021). "In this sense, it would be particularly useful to determine if increased resistin values in a horse with metabolic syndrome may have any predictive value for detecting the risk of laminitis." (PMID 35011183, 2021). "Horses with severe ID showed an elevation in resistin that may be secondary to the inflammatory status associated with metabolic syndrome." (PMID 35011183, 2021). "Thus, reduced PPARγ activity in APL cells decreased leptin but increased resistin expression, causing lipid metabolism disorder in hepatocytes and subsequent dyslipidemia in mice." (PMID 32929351, 2020).
metabolic syndrome (continued). "In this study, we first showed a significant increase of miR-let7e gene expression in OA chondrocyte cultures stimulated with visfatin and resistin suggesting that miR-let7e contributes to explaining the high association between metabolic syndrome, cardiovascular disease, and OA." (PMID 30563239, 2018). "Finally, low resistin levels have been associated with low prevalence of metabolic syndrome and healthier centenarians." (PMID 26922388, 2016). "The aim of this study was to determine the relationship between clinical and radiological hand osteoarthritis (OA) severity and serum resistin levels in women diagnosed with metabolic syndrome (MetS)." (PMID 40104308, 2025). "These composite indices correlate significantly with dyslipidemia, glycemic dysfunction, and subclinical inflammation, reflecting resistin’s synergistic interactions with metabolic derangements." (PMID 41347124, 2025). "Elevated levels of visfatin and resistin have been observed in women with metabolic syndrome, and they correlate with increased tumor aggression." (PMID 41375041, 2025). "Patients with metabolic syndrome have higher resistin concentrations compared to healthy individuals." (PMID 37048072, 2023). "Adiponectin, leptin and resistin belongs to the group of apparent serum markers of metabolic syndrome." (PMID 36826001, 2023). "Under specific environmental conditions (high fructose/sucrose or folate deficient diets) or after genetic modification (e.g., when expressing resistin or CRP transgenes), SHR animals also develop disturbances associated with metabolic syndrome." (PMID 35203486, 2022). "Pro-inflammatory adipokines (leptin and resistin) and pro-inflammatory cytokines (IL-1 β) were considered as potential metabolic syndrome serum markers." (PMID 35779187, 2022). "Further, the levels of key biomarkers of metabolic syndrome, leptin, resistin, adiponectin, PAI-1, and ghrelin were measured." (PMID 34579036, 2021). "Animal studies show that metabolic syndrome induces a deterioration in erectile function with the over expression of resistin and suppression of endothelial nitric oxide synthase (eNOS) activity in rat penile tissue." (PMID 34684698, 2021). "Intra-abdominal fat also secretes adipocytokines, such as leptin, adiponectin, resistin, and interleukins (IL-1 and IL-6), which act as energy regulators and inflammatory markers and are thus correlated strongly with metabolic syndrome." (PMID 32309767, 2020). "Thus, galectin-12, resistin, leptin, and other adipokines/cytokines regulated by PPARγ may act synergistically to affect lipid metabolism in metabolic tissues, contributing to the dyslipidemia associated with APL." (PMID 32929351, 2020). "Here, we identified that APL cells with defective PPARγ function is likely the essential factor triggering the dyslipidemia of APL patients by secreting resistin and subsequently disrupting the lipid metabolism of hepatocytes." (PMID 32929351, 2020). "The plasma levels of resistin have a positive correlation with HF, obesity and metabolic syndromes in which the activity of sympathetic nerve increases." (PMID 32440321, 2020). "The results provided new and potentially important insight regarding neural transmission when the plasma level of resistin increases; this reveals the role of resistin in cardiovascular responses such as metabolic syndrome and hypertension." (PMID 32440321, 2020). "Various inflammation markers including NFκβ, TNFα, interleukin-6 (IL-6), monocyte chemoattractant protein (MCP-1), visfatin, resistin, leptin and adiponectin have been identified in the metabolic syndrome pathogenesis." (PMID 31462242, 2019). "Plasma resistin was correlated to cardiovascular and pro-inflammatory markers and several components of the metabolic syndrome in obese adolescents." (PMID 26474157, 2015). "The focus of resistin research expanded from T2DM and metabolic syndrome to look at inflammatory-associated conditions." (PMID 26097512, 2015).
metabolic syndrome (continued). "More closely, increasing levels of resistin are correlated with an increase in pro-inflammatory cytokines, in particular in patients with metabolic syndrome." (PMID 26097512, 2015). "The authors intended to determine the relationship between resistin and insulin sensitivity, body fat distribution and the metabolic syndrome in humans." (PMID 24692844, 2014). "Generally speaking, the accumulation of visceral fat due to metabolic syndrome will lead to over-expression of adipokines, such as resistin, IL-6, and TNF-α, resulting in diminish eNOS activity, less NO generation and endothelial dysfunction." (PMID 23029112, 2012). "In patients with metabolic syndrome, thiazolidinediones (TZDs) including pioglitazone and rosiglitazone treatment markedly increased adiponectin and decreased resistin levels." (PMID 21251282, 2011). "The aim of this study is to establish interactions between the GLP-1 plasma levels and metabolic syndrome clusters and adipokines profile (leptin, adiponectin, resistin) and proinflammatory cytokines (TNFα, IL-6, IL1β, IL-17) in diabetic subjects with or without MAFLD." (PMID 41683648, 2026). "Some European studies uncovered a strong association between higher resistin levels and metabolic syndrome components, but this finding was not replicated in a US-based cohort." (PMID 40362681, 2025). "In humans, resistin strongly correlates with atherogenic dyslipidemia—characterized by elevated triglycerides and reduced high-density lipoprotein cholesterol—and promotes hepatic very-low-density lipoprotein (VLDL) secretion via sterol regulatory element-binding protein-dependent mechanisms." (PMID 41347124, 2025). "In addition, patients with metabolic syndrome and vitamin D insufficiency demonstrate increased resistin concentrations." (PMID 39519480, 2024). "In addition, resistin has a high plasma level in metabolic syndrome, obesity, and CV disorders such as hypertension and HF." (PMID 38164476, 2024). "Moreover, resistin increases the synthesis of apolipoprotein B and thus accelerates the process of atherosclerosis by inducing dyslipidemia with high LDL, triglycerides and low HDL concentrations." (PMID 37048072, 2023). "The study by Norman reported the negative impact of high resistin concentrations on eGFR, similar to the impact on systolic blood pressure, which was stronger than conventional risk factors such as metabolic syndrome." (PMID 37048072, 2023). "Although the correlation between asthma and metabolic syndrome needs to be cleared, it may be influenced by various factors, including high BMI, increased resistin levels, dyslipidemia, and mitochondrial dysfunction." (PMID 37108123, 2023). "In this context, HIT has been shown to induce positive modulation (decrease in inflammatory adipokines such as resistin, leptin and ghrelin, and increase the anti-inflammatory cytokines such as adiponectin) of adipokine profiles in postmenopausal women with metabolic syndrome." (PMID 37576981, 2023). "Recently discovered associations of resistin with carotid artery atherosclerosis and markers of chronic renal failure in patients with different levels of GFR and metabolic syndrome confirm the active role of resistin in the manifestation of diffuse atherosclerotic damage." (PMID 37623488, 2023). "Elevated resistin levels were also detected in murine and human atherosclerotic lesions and in the serum of premature coronary artery disease patients, suggesting that resistin plays a role in cardiovascular disease and metabolic syndrome." (PMID 35056647, 2022). "The aims of the present study were to quantify plasma resistin concentrations and their relationship with related parameters in healthy horses, in horses with metabolic syndrome/insulin dysregulation, and in horses with acute inflammation, in order to evaluate the usefulness of resistin." (PMID 35011183, 2021).
metabolic syndrome (continued). "Our results suggest that resistin may exacerbate NAFLD in metabolic syndrome through upregulating inflammatory cytokines and hepatic PEPCK and SREBP-1c." (PMID 25922835, 2015). "Interestingly, overexpression of resistin led to an inhibition of the production of IL-10, which limits inflammatory responses and promotes insulin sensitivity and is also down-regulated in metabolic syndrome." (PMID 16854242, 2006). "SdLDL and resistin level observed to be positively connected with BMI, HbA1c, systolic and diastolic blood pressure, triglycerides (TG), total cholesterol, VLDL, and LDL levels, while showed negative association with HDL level suggesting potential contributory factor for dyslipidemia." (PMID 41315571, 2025). "Furthermore, whether inhibition of resistin with antiresistin RNA oligo ameliorates HFD-induced metabolic syndrome and NAFLD and the possible molecular mechanisms were investigated." (PMID 25922835, 2015). "Other studies also confirmed that the levels of resistin corelate with cardiac fibrosis and that resistin is an independent predictor of LVR in patients with STEMI and metabolic syndrome at 12 months follow up." (PMID 35204357, 2022). "Adiponectin, leptin, resistin, TNF-α and IL-6 are considered as possible serum markers of metabolic syndrome and their expression levels are majorly regulated by SREP-1c and PPAR-γ." (PMID 33917607, 2021). "Moreover, after the administration of vaspin, mRNA expression levels of genes associated with metabolic syndrome (MetS) (GLUT4, resistin, adiponectin and leptin) returned to normal levels in obese rats’ WAT." (PMID 34359881, 2021). "In line with a previous finding that resistin serum levels were significantly correlated with the inflammatory chemokines such as MCP-1 and RBP4, which are major players in the pathogenesis of metabolic syndromes." (PMID 29785210, 2018). "We have demonstrated that selected inflammatory and anti-inflammatory markers (CRP, adiponectin, leptin, resistin, and Lp-PLA2) are involved in both pathogenesis of metabolic syndrome and pathogenesis of psoriasis." (PMID 28097156, 2016). "We found a positive correlation between resistin serum levels and PAI-1 serum levels in severely burned children, just like other studies reported the same type of correlation in metabolic syndrome and myocardial infarction." (PMID 39062875, 2024). "There were significant differences (p < 0.05) in leptin, resistin, and visfatin as well as significant dyslipidemia among those with GDM compared to those without GDM." (PMID 31836012, 2019). "Interestingly, regulation of hepatic LDL receptors by resistin involves the related PCSK family member PCSK9, recently identified as a novel target in patients suffering from severe dyslipidemia." (PMID 23936445, 2013). "Resistin, an important adipokine, upregulates fatty acid oxidation (FAO) in synovial cells via the CAP1/PKA/CREB signaling pathway, thereby promoting inflammation and a catabolic phenotype that further exacerbates the progression of metabolic syndrome-related knee OA (MetS-KOA)." (PMID 41245401, 2025). "However, as all patients from the present study have metabolic syndrome characterized by a chronic pro-inflammatory state, differences in the degree of adherence to MDP may not be enough to reflect changes in resistin levels." (PMID 35624765, 2022).
atherosclerosis (122 papers, 2004 to 2025). A disease characterized by the build-up of fatty material and calcium deposition in the arterial wall resulting in partial or complete occlusion of the arterial lumen. "It was concluded that higher serum resistin (Inflammatory marker of atherosclerosis) concentration is associated with CVDs61." (PMID 39962072, 2025). "Elevated circulating resistin levels are strongly associated with atherosclerosis severity and adverse clinical outcomes." (PMID 41347124, 2025). "In this context, our findings highlight the potential role of resistin as a diagnostic and therapeutic parameter in the management of atherosclerosis." (PMID 39635208, 2024). "The biomarker resistin is likely to be an indicator of a unique relationship between metabolic signals, atherosclerosis, and inflammation that is associated with human atherosclerosis." (PMID 38227584, 2024). "We previously reported that resistin is a causal factor of atherosclerosis by inducing adhesion molecules on endothelial cells and monocytes." (PMID 39050819, 2024). "It is known that not only the ECS but also resistin is associated with the process of atherosclerosis." (PMID 39050819, 2024). "Prior research has shown resistin to be a harbinger of atherosclerosis, seemingly implicated in its pathogenesis via vascular endothelial dysfunction, vascular smooth muscle cell (VSMC) proliferation, and foam cell transformation." (PMID 37763771, 2023). "As resistin has been suggested as a marker of the severity of myocardium ischemic injury, the change of resistin by CoQ10 in dyslipidemic patients indicated a further decreased risk for them to develop atherosclerosis." (PMID 35241098, 2022). "Resistin is produced by adipose tissue, and a high circulating concentration of resistin is associated with a higher risk of atherosclerosis." (PMID 35208189, 2022). "Adipokines, including adiponectin, leptin, resistin, omentin, visfatin, chemoattractant and retinol binding protein 4, are considered to be risk factors for atherosclerosis." (PMID 34122426, 2021). "Emerging evidence suggests that recombinant resistin directly causes endothelial dysfunction, implying a potential role in atherosclerosis." (PMID 34886472, 2021). "Treatment with β-OHB reduced aortic plaque formation without affecting blood lipid profiles and decreased serum production of resistin, a well-established risk factor for both AD and atherosclerosis." (PMID 32069870, 2020). "Expression of resistin from inflammatory blood cells augmenting release of cytokines and causing sub-endothelial damage reveals its association with subclinical atherosclerosis resulting in hypertension and CAD." (PMID 31258568, 2019). "While resistin levels correlate with traditional cardiovascular risk factors, their direct association with carotid intima-media thickness, a marker of subclinical atherosclerosis, remains unclear." (PMID 40137170, 2025). "Considering that CIMT is a well-established marker of subclinical atherosclerosis and, by extension, an indicator of cardiovascular risk, these findings suggest that resistin may play a significant role in cardiovascular pathology." (PMID 40077669, 2025). "We also included resistin as a comparison as it showed some association with atherosclerosis." (PMID 37512134, 2023). "In contrast, increased resistin increases the risk of T2D and atherosclerosis." (PMID 35831939, 2022). "Among them, leptin, resistin, visfatin, chemoattractant and retinol binding protein 4 may be the common pathogenic factors of psoriasis and atherosclerosis." (PMID 34122426, 2021). "It is reported that human macrophages secrete resistin on their own, and this contributes to atherosclerosis development directly by causing endothelial and smooth muscle cell (SMC) dysfunction, potentially increasing the permeability of LDL into adjacent tissue." (PMID 32947976, 2020).